EOLA1 (endothelium and lymphocyte associated ASCH domain 1)
Description:
May play a role in cell protection during the inflammatory response. In epithelial cells, negatively regulates IL6 production and apoptosis through the regulation of MT2A expression.
Synonyms: CXorf40; CXorf40A
Tractability: No criterion of Open Targets' tractability assessment is met for any kind of drug.
Gene: Protein-coding gene on chromosome X (149,536,605 to 149,550,510, forward strand). Ensembl gene ENSG00000197620.
Gene Ontology:
Molecular function: protein binding
Biological process: regulation of gene expression; regulation of interleukin-6 production
Cellular component: mitochondrion
Homologues: Orthologues: chimpanzee EOLA2 (97% identical), macaque EOLA2 (93% identical), macaque EOLA1 (83% identical), rat Eola2 (80% identical), dog EOLA1 (79% identical), mouse Eola1 (77% identical). Paralogues in human: EOLA2 (99% identical).
Diseases named in the same sentence as EOLA1 in open-access papers:
EOLA1 is named in the same sentence as 2 diseases in open-access papers, as found by Europe PMC text mining. Sharing a sentence is not in itself a finding about the gene and the disease. The quoted sentences say what the papers report.
infection (1 paper, 2014). The state of being infected such as from the introduction of a foreign agent such as serum, vaccine, antigenic substance or organism. "The cells with depletion of EOLA1 were treated with LPS (100 ng/ml) at the point of 48 h infection and IL6 was detected by ELISA assay 24 h after LPS induced." (PMID 24916366, 2014). "The cells with depletion of EOLA1 were treated with LPS (100 ng/ml) at the point of 48 h post-infection and IL6 was detected by ELISA assay 6 h after LPS induced." (PMID 24916366, 2014).
EOLA1 also shares sentences with these, for which no sentence is quoted: Diabetic Foot Ulcer (1 paper).